MUC4 (mucin 4, cell surface associated)
Diseases named in the same sentence as MUC4 in open-access papers (continued):
Sharing a sentence is not in itself a finding about the gene and the disease.
breast carcinoma (54 papers, 2008 to 2024). "MUC4 is a glycoprotein that is often aberrantly overexpressed in breast cancer and associated with lymph node metastases." (PMID 36291900, 2022). "Results from our team demonstrate that TNFα expression and secretion by tumor cells is implicated in the resistance of HER2+ breast cancer cells to T-DM1 therapy by the upregulation of MUC4." (PMID 33540543, 2021). "MUC4 has been described to promote blood cell association with tumor cells and to be involved in metastasis formation in a breast cancer mouse model." (PMID 32604718, 2020). "Emerging evidence suggests that MUC4 mucin is associated with metastasis of various cancers, including breast cancer." (PMID 23408941, 2013). "An earlier study reported that there is a high incidence of MUC4 expression in breast cancer, which is associated with metastatic disease." (PMID 23408941, 2013). "We chose to investigate Muc4 as a potential direct transcriptional target of Elf5 since Muc4 has a role in the pregnant mammary gland in rodents and in humans and dysregulated expression of MUC4 has been associated with breast cancer." (PMID 20949099, 2010). "Although there is a high incidence of MUC4 expression in breast cancer and a significant association with metastatic disease, limited information is available regarding its functional role(s) in breast cancer especially in the triple negative sub-type." (PMID 23408941, 2013). "In addition, Muc4 has been shown to impart resistance to the trastuzumab chemotherapeutic agent in breast cancer cells by causing steric interference with the drug." (PMID 19738614, 2009). "Interestingly, in a xenograft model of ER(+)/HER2 overexpressing breast cancer, the loss of the ER protein and deregulation of the progesterone receptor with increased mucins, especially MUC4, which has been associated with endocrine resistance in breast cancer, has been observed." (PMID 23344024, 2012). "Breast cancer cells that make too much HER2/ERBB2 spread faster but are also more likely to respond to HER-specific chemo and immunotherapy, with mutations in MUC4 known to associate with upregulated ERBB proteins, observed in the Indian cohort." (PMID 37091785, 2023). "On the one hand, MUC4 is a glycoprotein of the mucin family that has been found to be capable of detecting HER2-positive breast cancer response to trastuzumab in a specific manner." (PMID 36276152, 2022). "Among them, TNFα-induced mucin 4 (MUC4) expression elicits trastuzumab resistance in HER2-positive JIMT-1 breast cancer models." (PMID 35890234, 2022). "Further, we constructed PRDM16 overexpression vector to confirm the regulatory effect of PRDM16 on MUC4 levels in breast cancer cells, and the efficiency was tested by qRT-PCR assay." (PMID 36309503, 2022). "We have also demonstrated that blockade of tmTNFα and sTNFα with etanercept downregulates the membrane glycoprotein mucin 4 (MUC4) expression and overcomes trastuzumab de novo or acquired resistance in HER2+MUC4+ breast cancer cells and xenografts." (PMID 33540543, 2021). "To our knowledge, we are the first group to report that TNFα increases MUC4 expression through activation of the NF-κB pathway in HER2-positive breast cancer." (PMID 32391269, 2020). "In particular, in HER2-positive breast cancer, MUC4 expression impairs trastuzumab efficacy by masking the binding epitope in the HER2 molecule and is an independent biomarker of poor survival in patients treated with adjuvant trastuzumab." (PMID 32391269, 2020). "Our team also contributed to the characterization of MUC4 expression in different histological breast cancer subtypes." (PMID 32391269, 2020). "First, the endogenous expression of TTP and MUC4 were examined in gastric and breast cancer cell lines using qRT-PCR and western blotting." (PMID 31141941, 2019).
breast carcinoma (continued). "In particular, we have proved that tumor necrosis factor alpha (TNFα) drives MUC4 expression in HER2-positive breast cancer through the activation of NF-kB transcription factor." (PMID 29281999, 2017). "We also proved that MUC4 expression is associated with resistance to adjuvant trastuzumab administration and chemotherapy in HER2-positive breast cancer patients." (PMID 29281999, 2017). "Elevated MUC4 expression increases aggression of breast cancer, including decreased binding of breast cancer tissues to extracellular structures such as laminin, fibronectin, and collagen and reduced cell-cell interactions among these structures." (PMID 27829225, 2017). "We compared MUC4 expression in IMPC with respect to other histological breast cancer subtypes by immunohistochemistry." (PMID 29281999, 2017). "IMPC appeared as the histological breast cancer subtype with the highest MUC4 expression compared to IDC, lobular and mucinous carcinoma." (PMID 29281999, 2017). "In breast cancer, the post-transcriptional regulation of MUC4 is lost when cancer cells become unresponsive to TGF signals, most likely as a result of ErbB2 overexpression." (PMID 27829225, 2017). "We have recently demonstrated that mucin 4 (MUC4) expression in HER2-positive breast cancer is a biomarker of poor prognosis in patients treated with trastuzumab in the adjuvant setting." (PMID 29281999, 2017). "MUC4, a membrane glycoprotein, promotes metastasis given its ability to confer anti-adhesive properties to breast cancer cells." (PMID 29281999, 2017). "The opposite is true for other genes, like TTN, MUC4 and RYR2, which are amongst the most frequently mutated genes in breast cancer, but were clearly deprioritized by SomInaClust." (PMID 25903787, 2015). "FAK pathway is essential for the motility or migration of cancer cells, which was correlated with MUC4 expression in pancreatic, ovarian and breast cancer cells." (PMID 25686822, 2015). "These preliminary studies provide a strong rationale to undertake a future study in a larger sample set to determine the association of MUC4 with TNBC and other breast cancer sub-types." (PMID 23408941, 2013). "A subsequent report showed increased expression of Muc4 in JIMT-1 HER2-overexpressing breast cancer cells which display primary resistance to trastuzumab versus sensitive cell lines." (PMID 23227361, 2012). "More recently, upregulation of mucins including Muc4 was reported in ER-positive/HER2-positive breast cancer xenografts that had acquired resistance to trastuzumab plus lapatinib." (PMID 23227361, 2012). "Muc4 is a glycoprotein located within the membrane of secretory epithelial cells and its expression is dysregulated in breast cancer." (PMID 20949099, 2010). "The human breast carcinoma cell line T47D was used since it expresses MUC4 and therefore contains all the factors required for MUC4 expression." (PMID 20949099, 2010). "Together, these results suggest that the 1G8s preparation specifically recognizes human MUC4 in breast cancer cells, and will be useful in the analysis of human breast tissue samples." (PMID 19761616, 2009). "Rat Muc4 also provided resistance to chemotherapeutic agent cisplatin in melanoma and breast cancer cells." (PMID 19738614, 2009). "Further, another membrane-bound mucin MUC1 and rat Muc4 have also been shown to inhibit apoptosis induced by multiple insults in rat 3Y1 fibroblast cells and human melanoma and breast cancer cells, respectively." (PMID 19738614, 2009). "Membrane-bound mucin MUC1 and rat Muc4 have been shown to inhibit apoptosis induced by multiple insults in rat 3Y1 fibroblast cells and human melanoma and breast cancer cells, respectively." (PMID 19738614, 2009). "Quantitative RT–PCR analysis of MCF-7 breast cancer cells showed that treatment with 5-AzadC or TSA gave a greater increase in MUC4 mRNA compared to treatment with 5-AzadC/TSA in combination (38.9-, 30.9- and 6.03-fold increases, respectively)." (PMID 19127263, 2009).
breast carcinoma (continued). "Moreover, we have proved that MUC4 is an independent biomarker of poor disease-free survival in HER2+ breast cancer patients treated with adjuvant trastuzumab." (PMID 37284199, 2023). "This is consistent with previous reports that mutant MUC4 was correlated with higher TMB and potentially associated with prognosis in pancancer, while XIRP2 mutation was potentially associated with metastasis in breast cancer." (PMID 35402515, 2022). "In HER2-positive human breast cancer and gastric cancer cells, trastuzumab resistance is induced by high expression of MUC4 through the NF-κB pathway to reduce the effectiveness of ADCC (antibody-dependent cell-mediated cytotoxicity) in breast cancer cells and then induce drug resistance." (PMID 36276152, 2022). "However, in breast cancer (HR = 0.83, p = 0.0014) and colorectal cancer (HR = 0.02, p = 0.0456), increased expression of MUC4 was significantly correlated with good survival." (PMID 34336844, 2021). "Moreover, we disclosed that it is sTNFα and not tmTNFα that drives MUC4 expression; we observed that HER2+MUC4+ breast cancer cells and tumors were also sensitized to trastuzumab in combination with INB03." (PMID 33540543, 2021). "We identified that the invasive micropapillary carcinoma of the breast (IMPC), a low-incidence entity of breast cancer, was the one that had higher MUC4 expression in contrast to the infiltrating ductal carcinoma, the infiltrating lobular carcinoma or the mucinous carcinoma." (PMID 32391269, 2020). "In addition, we proved that MUC4 expression in breast cancer specimens is an independent prognostic biomarker of poor response to adjuvant trastuzumab." (PMID 32391269, 2020). "Only a few reports have thus far addressed the significance of MUC4 in breast cancer." (PMID 27846863, 2016). "For example, in one breast cancer study, silencing MUC4 led to reduced expression of HER2, although the molecular mechanism of this interaction is unknown." (PMID 24947164, 2014). "However, inadequate information is available regarding the functional role(s) of MUC4 mucin in breast cancer especially in TNBC." (PMID 23408941, 2013). "Overexpression of Muc4 has been reported in some aggressive mammary tumors." (PMID 23227361, 2012). "In our study we develop a preparation of the 1G8 antibody that specifically recognizes MUC4β by immunoblotting, and whose immunoreactivity with cultured MUC4-positive breast cancer cells by immunohistochemical staining is markedly suppressed when MUC4 expression is knocked down." (PMID 19761616, 2009). "To determine whether MUC4 expression is dysregulated in human breast tumors, we first immunoblotted tissue lysates of primary tumor samples from breast cancer patients with the 1G8s preparation." (PMID 19761616, 2009). "However, we observed that 1G8 obtained from a commercial source, which we call 1G8c, recognized a very prominent non-specific band of about 135 kDa in all cell lines, but only weakly recognized rat MUC4 inducibly expressed in human MCF7 breast cancer cells." (PMID 19761616, 2009). "Moreover, MUC4 expression in cancer specimens would help select the subgroup of HER2-positive breast cancer patients that benefit from the combination of anti-TNFα therapies with the standard treatments, as we previously demonstrated in HER2-positive breast cancer." (PMID 32391269, 2020). "The binding between trastuzumab and HER2 may be disrupted by the membrane-associated glycoprotein mucin-4 (MUC4), as evidenced by the overexpression of MUC4 in a trastuzumab-resistant breast cancer cell line and subsequent restoration of trastuzumab binding through MUC4 siRNA knockdown." (PMID 22649737, 2012). "MUC4 is highly expressed in breast cancer, and AFPRs were first isolated from the human MCF-7 breast cancer cell line." (PMID 33718192, 2021).
breast carcinoma (continued). "Our novel mutations in NCOR1, MUC4, and MUC16 genes should be validated in further mechanistic studies and translational studies so that those mutations might serve as predictive biomarkers or therapeutic targets for patients with CDK4/6 inhibitor-resistant breast cancer." (PMID 33504001, 2021). "Two cell lines (AGS and MDA-MB231; gastric and breast cancer cells) with low levels of TTP expression and high levels of MUC4 expression were selected and used in subsequent experiments." (PMID 31141941, 2019). "To compare MUC4 expression in IMPC with respect to other histological breast cancer subtypes, we performed IHC staining on an independent cohort of 113 breast cancer samples used as control." (PMID 29281999, 2017). "In breast cancer, most tumors express MUC1 and MUC3, and the expression of MUC2, MUC4, MUC5AC, and MUC6 is variable or limited." (PMID 27846863, 2016). "We have described clinicopathological characteristics of patients with breast cancer containing SRCs in relation to the expression levels of MUC1, MUC2, MUC4, MUC5AC, and MUC6." (PMID 27846863, 2016). "Relevant to this, Marcato and Lee's groups have demonstrated that ALDH1A3-mediated modulation of RA-target genes contributes in vivo protumorigenic properties including the transcription of the MUC4 oncogene, to MDA-MB-231 breast cancer cells." (PMID 25868979, 2015). "However, the functional role of MUC4 remains unclear in breast cancers, especially in TNBCs." (PMID 23408941, 2013). "In the T47D breast cancer cell line, exogenous addition of ELF5 was able to induce expression from the MUC4 promoter." (PMID 20949099, 2010). "We demonstrated that MUC4 acts as a physical barrier for immune exclusion in TNBC and HER2+ breast cancer, since tumor samples from patients with MUC4+ tumors evidenced scarce or null presence of TILs, while patients with MUC4- tumors evidenced abundant TILs on their TME." (PMID 37284199, 2023). "Our team has demonstrated that soluble TNFα (sTNFα) secretion by HER2+ breast cancer cells induces resistance to the anti-HER2 therapy trastuzumab, by upregulating the expression of the transmembrane glycoprotein mucin 4 (MUC4) through activation of the NF-kB pathway." (PMID 37284199, 2023). "Our group reported that TNFα-induced MUC4 is involved in HER2-targeted therapy resistance in vivo and in vitro, and that it is an independent predictor of trastuzumab response in HER2-positive breast cancer patients." (PMID 37284199, 2023). "On the other hand, TNFα blockers can inhibit the expression of MUC4 and then overcome the resistance of primary trastuzumab in HER2-positive breast cancer, and may also be used as a potential new therapeutic target." (PMID 36276152, 2022). "These include FAM183A, which is upregulated in breast cancer cells in response to Notch signaling; MUC4, expressed in 95% of breast carcinomas; HSPB6, which is downregulated in breast cancer; and CCL28, which promotes breast cancer proliferation, tumor growth and metastasis." (PMID 33957961, 2021). "Since pathologists’ examination of our HER2-positive cohort revealed several IMPC cases, and because MUC4 and IMPC share several characteristics, we wanted to explore whether MUC4 expression could be a feature of this breast cancer subtype." (PMID 29281999, 2017). "Presence of MUC4 and MUC1-C has also been related with Herceptin resistance in breast cancer." (PMID 25261375, 2014). "Finally, shRNA-mediated knockdown was employed to assess the contribution of MUC4 to the cellular growth and malignancy properties of JIMT-1 breast cancer cells." (PMID 19761616, 2009). "Studies on rat MUC4 (SMC) have also demonstrated that MUC4-induced HER2/neu activation may be important in tumour growth and metastasis in rat mammary carcinoma cells." (PMID 18665193, 2008).
breast carcinoma (continued). "MUC4, QRICH2 and PR1L1 mutations were also detected in breast invasive carcinoma databases (TCGA, Cell 2015; TCGA, Nature 2012), but no further research or relationship between these genes and breast carcinomas were published." (PMID 38243319, 2024). "Furthermore, the expression of MUC4 in breast cancer cells decreases apoptosis 5-10-fold relative to nonmalignant breast cells." (PMID 27829225, 2017). "To support this hypothesis, we evaluated the cytotoxic activity of HER2bsFab against two different breast cancer cell lines, MCF-7 which weakly overexpresses HER2 and JIMT-1 which, although overexpressing HER2, displayed a low trastuzumab-binding capacity due to overexpression of mucin 4 (MUC4)." (PMID 24979648, 2014). "Interestingly, the binding site used by ELF5 to regulate MUC4 expression is the same site used by another Ets factor, PEA3, to regulate MUC4 expression in the pancreas, in HC11 mouse mammary epithelial cells and in MAT-B1 and MAT-C1 rat mammary tumour cells, suggesting some functional redundancy." (PMID 20949099, 2010). "In a preliminary screening of breast cancer cells, we observed that the invasive MDA-MB-231 TNBC cell line expressed MUC4 when grown in α-MEM media (left lane), while non-invasive TNBC cell lines BT-20 and MDA-MB-468 were MUC4 negative (data not shown)." (PMID 23408941, 2013).